CAV1 (caveolin 1)
Diseases named in the same sentence as CAV1 in open-access papers (continued):
Sharing a sentence is not in itself a finding about the gene and the disease.
gastric cancer (83 papers, 2008 to 2026). A primary or metastatic malignant neoplasm involving the stomach. "The expression of CAV1 in gastric cancer–associated fibroblasts and their corresponding inflammation-associated fibroblasts was used as a potential biomarker of gastric cancer progression." (PMID 34790582, 2021). "Patients receiving the CAV1 (rs7804372) TT haplotype had a higher gastric cancer risk and susceptibility than those with AT or AA haplotypes." (PMID 34128850, 2021). "In pancreatic and gastric cancers, the possible association between Cav-1 and SNAIL has been verified, albeit in opposing ways." (PMID 31297035, 2019). "We investigated Cav-1 in primary and metastatic tumor cells of gastric cancer (GC) and its association with clinical outcomes." (PMID 28828003, 2017). "In the present study, we observed a bidirectional alteration of Cav-1 expression in gastric cancers, which is linked to the mitogenic conversion of its function." (PMID 29141593, 2017). "In the present study, we observed that Cav-1 provokes either a growth-inhibiting or growth-promoting effect in gastric cancers, and this property of Cav-1 is associated with its reciprocal regulation of ERK." (PMID 29141593, 2017). "Collectively, these results indicate that the bidirectional alteration of Cav-1 expression in gastric cancers is linked to its opposite effects on tumor cell proliferation, which stems from the reciprocal control of the RAF-ERK negative feedback loop." (PMID 29141593, 2017). "A meta analysis showed that overexpression of CAV1 was associated with a better overall survival in gastric cancer patients." (PMID 29190968, 2017). "CAV1 deficiency in CAFs also led to increased production and secretion of pro-inflammatory and tumour-enhancing cytokines, contributing to proliferation and invasion of gastric cancer cells." (PMID 39780187, 2025). "Using proteomics and bioinformatics techniques, CAV1 has been identified as a major network-centric protein between gastric cancer-associated fibroblasts (GCAFs) and their corresponding inflammation-associated fibroblasts (GIAFs) which was later validated using IHC40." (PMID 33739025, 2021). "Chronic infection of gastric epithelial cells by Helicobacter pylori (H. pylori) is a major risk factor for human gastric cancer (GC) where Cav1 is frequently down-regulated." (PMID 23592983, 2013). "Other studies have found that the crosstalk between tumor cells and CAFs induced by CAFs autophagy can promote cancer progression, and low caveolin-1 (Cav-1, an autophagy marker) in CAFs can predict a shorter survival time of gastric cancer." (PMID 40485724, 2025). "FTO enhanced the proliferation and metastasis of gastric cancer cells via potentiating caveolin-1 mRNA degradation." (PMID 40002690, 2025). "Low expression of CAV1 in CAFs was an independent predictor of poor prognosis in gastric cancer patients." (PMID 39780187, 2025). "FTO has been shown to augment the proliferation and metastasis of gastric cancer by modulating mitochondrial fission/fusion dynamics and metabolic processes, which involves the facilitation of caveolin-1 mRNA degradation via demethylation." (PMID 39869517, 2025). "An immunohistochemical (IHC) investigation assessed the expression levels of hub genes (SDC2, RGS4, SERPINE1, DUSP1, and CAV1) in gastric cancer." (PMID 39871942, 2024). "FTO was elevated in gastric cancer and showed an oncogenic effect by promoting cell proliferation and metastasis via inducing the degradation of caveolin-1 (CAV1) mRNA by demethylation." (PMID 38503745, 2024). "Polypyrimidine tract-binding protein 3 (PTBP3) increases the migration and invasion ability of gastric cancer cells through mediating CAV1 selective splicing." (PMID 39726754, 2024). "One recent study consistently showed that the deletion of m6A demethylase FTO depletion induces mitochondrial fission in gastric cancer cells via caveolin-1." (PMID 38549713, 2024).
gastric cancer (continued). "Here, we report that chemoresistant gastric cancer cells rely heavily on endocytosis, facilitated by caveolin-1, for survival." (PMID 37919422, 2023). "Downregulation of caveolin-1 alone was sufficient to induce cell death in SEM-type gastric cancer cells, emphasizing its importance as a survival mechanism." (PMID 37919422, 2023). "Consistently, chloroquine, a lysosomal inhibitor, successfully blocked caveolin-1-mediated endocytosis, leading to the marked suppression of tumor growth in chemorefractory gastric cancer cells in vitro, including patient-derived organoids, and in vivo." (PMID 37919422, 2023). "Caveolin-1 (Cav-1) is expressed less while induced by HIF-1, which regulates E-cadherin to cause the epithelial-mesenchymal transition (EMT) in gastric cancer." (PMID 37143652, 2023). "Together, our findings suggest that caveolin-1-mediated endocytosis is a key metabolic pathway for gastric cancer survival and a potential therapeutic target." (PMID 37919422, 2023). "caveolin-1 was highly upregulated in the most malignant stem-like/EMT/mesenchymal (SEM)-type gastric cancer cells, allowing caveolin-1-mediated endocytosis and utilization of extracellular proteins via lysosomal degradation." (PMID 37919422, 2023). "A new study reveals that Caveolin-1 (CAV1) is specifically expressed in the most malignant SEM-type gastric cancer (GC), and CAV1-driven endocytosis is a critical survival mechanism of malignant GC." (PMID 37919422, 2023). "Mechanistically, CAV1 accelerates gastric cancer progression via up-regulating the epithelial to mesenchymal transition under hypoxic conditions." (PMID 37642765, 2023). "Kundong Zhang reported that knockdown of CAV1 suppressed the expression of E-cadherin and enhanced cell migration ability in gastric cancer." (PMID 36147736, 2022). "In gastric cancer, for example, circCCDC9 exerts a tumor-suppressive effect through the miR-6792-3p/CAV1 axis and is significantly related to the tumor size, infiltration of the lymph node, and overall survival of GC patients." (PMID 35682879, 2022). "CircCCDC9 expression was significantly lower than normal in gastric cancer tissue samples, and the study confirmed that circCCDC9 inhibits the progression of gastric cancer by regulating CAV1 in combination with miR-6729-3p." (PMID 36138829, 2022). "Cav-1 activated the Wnt/β-catenin pathway by promoting Met expression, thereby facilitating cisplatin resistance of gastric cancer cells." (PMID 34168559, 2021). "For example, circCCDC9 sponges miR-6792-3p to suppress the progression of gastric cancer through up regulating CAV1 expression." (PMID 34055775, 2021). "For example, circCCDC9 suppresses the progression of gastric cancer by regulating CAV1 via miR-6792-3p." (PMID 34012964, 2021). "circCCDC9, with low expression in gastric cancer tissues and cells, can attenuate the inhibitory effect on the target gene CAV1 after adsorbing miR-6792-3p, thereby inhibiting the proliferation, migration and invasion of gastric cancer cells." (PMID 33937077, 2021). "In gastric cancer cells, hypoxia (1% O2)-enhanced HIF1α stabilization coincides with the downregulation of CAV1 expression and epithelial–mesenchymal transition." (PMID 32825247, 2020). "Taken together, these findings demonstrated with first lines of evidence that circCCDC9 acted as a miR-6792-3p sponge to suppress the progression of gastric cancer through enhancing CAV1 expression." (PMID 32386516, 2020). "That being said, animal model of cisplatin resistance should be explored and used in further stduies to identify the chemoresistance-promoting role of Cav-1 in gastric cancer." (PMID 32117718, 2020). "Temporal modulation of CAV1 with the cholesterol-lowering drug lovastatin increases HER2 availability at the cell membrane to enhance the binding of trastuzumab to gastric cancer cells." (PMID 31171598, 2019).
gastric cancer (continued). "The reduced expression of caveolin-1 can promote the activation of gastric cancer-related fibroblasts, resulting in gastric cancer." (PMID 30424755, 2018). "In this study, we found that Cav-1 is abnormally down- and up-regulated in a considerable fraction of gastric cancers due to promoter hyper- and hypo-methylation, respectively." (PMID 29141593, 2017). "Mean LNR level was significantly higher in patients with gastric cancer with high metastatic tumoral Cav-1 expression (0.229 ± 0.195) compared to those with low metastatic tumoral Cav-1 expression (0.416 ± 0.255, P = 0.015)." (PMID 28828003, 2017). "Collectively, these findings indicate that up- and down-regulated Cav-1 in gastric cancers has opposite roles in the regulation of tumor cell growth." (PMID 29141593, 2017). "A substantial fraction of primary tumors and cell lines displayed abnormally low or high Cav-1 mRNA expression, indicating the bidirectional alteration of Cav-1 in gastric cancers." (PMID 29141593, 2017). "In gastric cancer, epithelial Cav-1 loss could promote malignant progression of gastric cancer, and Cav-1 loss in CAFs heralded worse outcome of gastric cancer patient, suggesting Cav-1 level in CAFs may be a candidate therapeutic target and a useful prognostic marker of gastric cancer." (PMID 28546853, 2017). "Collectively, these results indicate that Cav-1 is commonly down- and up-regulated in early and advanced gastric cancers, respectively, suggesting the oncogenic conversion of its function during tumor progression." (PMID 29141593, 2017). "In contrast, a recent study using quantum dots immunofluorescence histochemistry identified that epithelial Cav-1 expression gradually decreases with the progression of gastric cancer." (PMID 29141593, 2017). "Yuan's group found that epirubicin increased the activity of the human Wnt6 promoter through Cav1-dependent binding of β-catenin to the proximal Wnt6 promoter in gastric cancer, which is considered an important regulator of CSCs." (PMID 26431273, 2015). "Caveolin-1 promotes gastric cancer progression by up-regulating epithelial to mesenchymal transition by crosstalk of signalling mechanisms under hypoxic condition." (PMID 25948494, 2015). "CAV1 was also highly correlated with CE6, an ecosystem characterized by the enrichment of stromal features and cells that has been reported to be associated with worse prognosis features in gastric cancer." (PMID 38959243, 2024). "The selective splicing of CAV1 mediates the PTBP3-promoted metastasis of gastric cancer." (PMID 39726754, 2024). "For example, researchers found that the circRNA circCCDC9 functions as a tumor suppressor molecule in inhibiting the progression of gastric cancer through the miR-6792-3p/CAV1 axis; this provided a useful biomarker and therapeutic target for patients with gastric cancer." (PMID 33591945, 2021). "Moreover, our recently study demonstrated that circCCDC9 directly sponged miR-6792-3p to relieve the repressive effect of miR-6792-3p on its target CAV1, and then to suppress the progression of gastric cancer." (PMID 34656159, 2021). "Moreover, results from our early studies revealed that CAV1 acted as a critical role in the progression and metastasis of pancreatic cancer and gastric cancer." (PMID 32386516, 2020). "Targeted therapies against the activation of Cav-1-dependent WNT signaling might be developed to improve the extremely poor prognosis of gastric cancer patients with cisplatin-resistance." (PMID 32117718, 2020). "However, in gastric cancer, PTBP3 promotes metastasis of gastric cancer by regulating CAV1 and reduces the sensitivity of gastric cancer cells to 5-Fu by the HDAC6/Akt/TYMS pathway." (PMID 32477006, 2020).
gastric cancer (continued). "This schematic diagram shows our research content very intuitively: After being stimulated by RANKL, the transmembrane proteins EGFR and RANK form a complex with Cav-1 on the lipid raft platform, which further activates downstream signaling pathways and ultimately promotes gastric cancer migration." (PMID 31933009, 2020). "In summary, our findings provide experimental evidence that PTBP3 may function as a metastatic gene in gastric cancer by regulating CAV1 through alternative splicing." (PMID 29752441, 2018). "Moreover, clinical investigations have revealed that CAV1 expression is positively correlated with chemotherapy response in gastric cancer and non-small lung cancer." (PMID 30333750, 2018). "Previous IHC studies reported contrasting results on Cav-1 expression in gastric cancers." (PMID 29141593, 2017). "Our finding of Y97N mutation in the SNU638 cancer cell line thus raises the possibility that Cav-1 regulation of PKA signaling might be altered in these gastric cancer cells." (PMID 29141593, 2017). "Our data thus suggest that Cav-1 may act as a stage-specific growth modulator in gastric cancer, which is inactivated during the early stages of tumorigenesis and its subsequent elevation confers growth advantages and malignant progression." (PMID 29141593, 2017). "MicroRNA-103/107 have been identified as a invasive predictor of tumor relapse and overall survival for triple-negative breast cancer patients; additionally, microRNA-103/-107 also modulated multiple drug resistance in human gastric carcinoma by downregulating caveolin-1." (PMID 27409165, 2016). "Among them, CAV1 is found in the sub-membrane area and in the cytoplasm and it was already suggested that CAV1 might be a positive regulator of β-catenin in human gastric cancer cells." (PMID 26307673, 2015). "Cav-1 was positively associated with tumor stage and nodal status, and was inversely correlated with the response to ECF (epirubicin, cisplatin and 5-fluorouracil) chemotherapy administrated to gastric cancer patients." (PMID 26431273, 2015). "Correlations between Cav-1 expression and clinicopathological parameters of gastric cancer." (PMID 23527097, 2013). "Furthermore, reduction in caveolin-1 expression was observed at the mRNA and protein level for neoplastic mucosa samples from patients with gastric cancer and caveolin-1 expression was low in cell lines derived from primary tumours." (PMID 18400052, 2008). "In clinical research of gastric cancer (GC), as poor prognosis marker, the low expression of fibroblastic CAV1 is found with positive fibroblastic LC3B." (PMID 31014370, 2019). "Classes toSTAD and toTHCA can also be separated for gastric cancer with proteins characteristic to class toStad being Cyclin_B1, Caspase-7_cleavedD198, and Claudin-7 whereas toTHCA cases have significantly increased expression/phosphorylation of NF-kB-p65_pS536 and Caveolin-1." (PMID 30442178, 2018). "Among other upregulated genes, CAV1 was shown to be involved in EV formation and cargo sorting, particularly within hypoxic TME in gastric cancer." (PMID 39920655, 2025). "Moreover, the expression of CAV1 was negatively correlated with the overall survival of GC patients in the TCGA gastric cancer database." (PMID 37919422, 2023). "FTO accelerated cell growth and metastasis via regulation of caveolin-1 and ITGB1 and metabolic regulation of mitochondrial dynamics in gastric cancer." (PMID 36003776, 2022). "In contrast, knocking out Cav1 in gastric cancer cells increases the availability of HER2 at the cell surface, thus sensitizing gastric cancer cells to anti-HER2 therapy." (PMID 34207120, 2021). "In gastric cancer, PTBP3 contributes to the cancer metastasis by mediating CAV1 alternative splicing." (PMID 32117452, 2020). "However, the relationship between Cav-1 and chemoresistance in gastric cancer remains unknown." (PMID 32117718, 2020).
gastric cancer (continued). "We showed that pharmacological modulation of CAV1 with lovastatin increases membrane HER2 availability for binding of trastuzumab in breast and gastric cancer cells." (PMID 31171598, 2019). "To assess the efficacy of trastuzumab treatment when combined with CAV1 depletion in vivo, we conducted therapy studies in mice bearing NCIN87 gastric and BT474 breast, and gastric cancer PDXs." (PMID 30510281, 2018). "The aim of this study was to detect the expression of fibroblastic Cav-1 and LC3B, markers of autophagy, in gastric cancer (GC) and to analyze their clinical significances." (PMID 23203033, 2012). "Therefore, the study of Cav-1 and LC3B in the intercellular matrix is very important in gastric cancer patients, and this is necessary to further explore the tumor microenvironment." (PMID 41030451, 2025). "In keeping with this observation, a recent study in gastric cancer found a negative correlation between tumor CAV1 level and T-DM1 tumor uptake." (PMID 36831621, 2023). "In addition, Cav-1 also targeted WNT6, an activator of Wnt pathway, to induce chemoresistance to epirubicin in human gastric cancer cells." (PMID 34168559, 2021). "However, the mechanism of Cav-1 in the regulation of WNT pathway and the related chemoresistance in gastric cancer cells has not been fully understood." (PMID 32117718, 2020). "A recent study also revealed CAV1 depletion could stabilize HER2 at the cell surface, further to increase the tumor avidity for trastuzumab on HER2-positive gastric cancer." (PMID 32386516, 2020). "Overall, PTBP3 mediates CAV1 signalling through alternative splicing, and CAV1α has a negative effect on the metastasis potential of gastric cancer cells following integrin/Src/FAK pathway activation." (PMID 29752441, 2018). "In addition, Cav-1 overexpressing gastric cancer cell line gained prosurvival ability, which results are concordant with ours that the high Cav-1 expression of tumor cells in metastatic lymph node was related with poor prognosis of GC patients." (PMID 28828003, 2017). "The qRT-PCR experiments were designed to detect the expression levels of the top 5 ranking HAX1, RNF2, PIM3, TPP1 and CAV1 genes in addition to the seed proteins ABCB1, AKT1 and BCL2 in both the SGC7901 gastric cancer cell line and the Adriamycin resistant SGC7901/ADR cell line." (PMID 26039373, 2015). "However, the clinical significance of Cav-1 expression in gastric cancer (GC) remains largely unknown." (PMID 23527097, 2013). "Interestingly, however, caveolin-1 expression increased in cell lines derived from distant metastases, suggesting that stage-dependent fluctuations in caveolin-1 expression (initial suppression followed by re-expression at later stages) may contribute to the pathogenesis of gastric cancer." (PMID 18400052, 2008). "Based on our observations on the metastatic function of PTBP3 in this study, intertwining with the importance of CAV1 in tumour metastasis, we questioned whether the metastasis function of PTBP3 in gastric cancer was attributed to its suppressive effect on CAV1α expression by alternative splicing." (PMID 29752441, 2018). "The highly expressed circRNA BIRC 6 (circBIRC 6) in gastric cancer (GC) patients can increase Cav-1 expression by regulating the miR-488-glutamate ionotropic receptor N-methyl-D-aspartate type subunit 2D (GRIN2D) axis, thereby inhibiting autophagy and promoting GC progression." (PMID 41030451, 2025).